EDNRB (endothelin receptor type B)
Diseases named in the same sentence as EDNRB in open-access papers (continued):
Sharing a sentence is not in itself a finding about the gene and the disease.
microcephaly (1 paper, 2021). A congenital or acquired developmental disorder in which the circumference of the head is smaller than normal for the person's age and sex. "Moreover, our results are consistent with the fact that the depletion or low EDNRB expression leads to defective B cell differentiation or intrinsic lymphoid defects, similar to that MBP reduction causes neurodegenerative disorders like microcephaly." (PMID 33891593, 2021).
myeloma (1 paper, 2024). "This previously reported restricted expression pattern of EDNRB in myeloma cells is in accordance with our findings and explains the high fold change of EDNRB gene that we identified." (PMID 38690165, 2024).
neuroblastoma (1 paper, 2023). Neuroblastoma (NB) is the most common solid, extracranial childhood tumor. "To ascertain how many of the gut developmental TFs we identified, control RET and EDNRB, we performed siRNA-mediated knockdown of each in the human neuroblastoma cell line SK-N-SH." (PMID 37948459, 2023). "We show that their knockdown in human neuroblastoma SK-N-SH cells reduces RET and/or EDNRB gene expression, expanding the RET-EDNRB GRN." (PMID 37948459, 2023).
neutropenia (1 paper, 2023). A decrease in the number of neutrophils found in the blood. "In our study, expression of EDNRB in SCI was significantly upregulated and correlated positively with neutrophils, indicating that EDNRB may also play a role in neutropenia." (PMID 37063890, 2023).
oral cavity cancer (1 paper, 2021). A primary or metastatic malignant neoplasm involving the oral cavity. "EDNRB promoter methylation, which is associated with the histologic diagnosis of premalignancy and the presence of malignancy, may be a promising marker for the early detection of premalignant lesions in oral cavity cancer." (PMID 33867351, 2021).
systemic lupus erythematosus (1 paper, 2015). An autoimmune multi-organ disease typically associated with vasculopathy and autoantibody production. "It has also been described for HERV-E.FABP7 in leukemic B cells; HERV-E.PTN, HERV-E.EDNRB, and HERV-E.MID1 in placenta but not in blood cells; and HERV-E clone 4-1 in peripheral blood lymphocytes (CD4+, CD8+ and B cells) but not in neutrophils from patients with systemic lupus erythematosus (SLE)." (PMID 25785516, 2015).
tongue SCC (1 paper, 2020). "We next determined whether combination treatment with EDNRB gene therapy and macitentan would inhibit neck metastasis in a mouse tongue SCC model established using the Hela-O3 cell line." (PMID 33257729, 2020).
ZIKV infection (1 paper, 2021). "We found that PTBP1, LIF, GHR, and PTBP3 were upregulated while EDNRB and MBP were downregulated upon ZIKV infection." (PMID 33891593, 2021). "Among the top selected differentially expressed genes, such as PTBP1, LIF, GHR, PTBP3, EDNRB, and MBP, the mRNA and protein expressions were confirmed to identify the dysregulation of the transcriptome in MPAs upon ZIKV infection." (PMID 33891593, 2021). "Our results showed that mRNA levels of PTBP1, LIF, PTBP3, and GHR were significantly upregulated, while EDNRB and MBP were downregulated upon ZIKV infection at indicated time." (PMID 33891593, 2021).
tumor (96 papers, 2002 to 2026). "Next, we asked whether patient tumor samples from The Cancer Genome Atlas (TCGA) showed an association between EDNRB mRNA expression and AKT activation." (PMID 32201539, 2020). "EDNRB functions as an immune regulator within the TME, contributing to immune evasion and angiogenesis via tumor-associated macrophages." (PMID 40892354, 2025). "Known biological functions of EDNRB include regulating cell proliferation, migration, and metabolic processes, with particular relevance to its anti-tumor characteristics in cancer biology." (PMID 40589973, 2025). "In prior literature, implicated overlapping genes, including WASF3, EDNRB, SOX10, BAMBI have been implicated in processes including tumor progression, migration, and invasion." (PMID 38857306, 2024). "Overexpression of EDNRB demonstrated inhibitory effects on tumor cell growth, migration, and invasion, likely mediated through activation of the cGMP-Protein Kinase G pathway." (PMID 38205153, 2024). "This includes elucidating the detailed mechanism of action of EDNRB in PCa, verifying its tumor suppressor effect in larger clinical sample sizes and diverse animal models, as well as investigating its impact on the prognosis of PCa." (PMID 38205153, 2024). "and EDNRB overexpression resulted in significant differences in tumor size, volume, and mass compared to the control group." (PMID 38205153, 2024). "Altered expression of EDNRB in cancer profoundly impacts tumor cell proliferation, migration, and invasion." (PMID 38205153, 2024). "Our study demonstrates the significant involvement of EDNRB in PCa, wherein it exerts inhibitory effects on tumor cell growth, migration, and invasion through the activation of the cGMP–PKG pathway." (PMID 38205153, 2024). "Among the identified interactions, we suggest EDN1/EDNRB as a putative novel tumor/endothelial cell interaction, and ANG/PLXNB2 and ANG/EGFR as putative new autocrine loops in ccRCC cancer cells." (PMID 38025776, 2023). "Higher immune inhibitor-associated genes like LAGs, VEGF, EDNRB, and TGFB1 were also upregulated, implying the critical role of lactate in a tumor immunosuppressive microenvironment." (PMID 37122693, 2023). "ReactomeFIViz enrichment analysis in Cytoscape showed an association of seven (EDNRB, CDKN2A, VEGFD, FOS, GNG11, TGFBR2, and BIRC5) of the forty-four nodes of the LC-BC CCPs with signaling pathways related with the acquisition of tumor characteristics." (PMID 36101460, 2022). "Endothelin receptor type B (EDNRB) is a member of the family of G-protein-coupled receptors, which plays a vital role in tumor cell proliferation, migration, and lymph angiogenesis via combination with endothelin-1." (PMID 35273656, 2022). "To assess the efficacy of targeting EDNRB signalling, we treated mice bearing A375 tumours either with BRAF inhibitor alone or a BRAF inhibitor/bosentan combination and found that growth was significantly reduced with the combination treatment." (PMID 28606996, 2017). "To evaluate the importance of EDNRB signaling for epilation-induced skin hyperpigmentation, we used homozygous EdnrblacZ/lacZ (Ednrb−/−) mice." (PMID 28779103, 2017). "Silencing of the EDNRB gene by DNA methylation during development of tumours results in the down-regulation of the receptor." (PMID 25131455, 2014). "EDNRB is a new candidate tumor suppressor gene which is often down-regulated or even silenced by promoter hypermethylation in various human cancers." (PMID 24326135, 2013). "During the development of tumor, EDNRB gene transcription is downregulated by promoter hypermethylated, and consequently alters the ET1 signaling pathway." (PMID 24326135, 2013). "One of the prioritised clones identified in the reverse library (i.e. the library containing sequences under-represented in the metastasising tumours) matched part of the EDNRB gene as determined by a standard BLAST (Basic linear alignment search tool) search." (PMID 12439722, 2002).
tumor (continued). "We have identified endothelin receptor type B as differentially expressed between these tumours and confirmed this observation using comparative multiplex RT–PCR." (PMID 12439722, 2002). "EDNRB activation inhibits natural killer cell function and promotes the accumulation of immunosuppressive cells like regulatory T cells and myeloid-derived suppressor cells in the tumor microenvironment." (PMID 39006665, 2024). "In vivo experiments further confirmed the tumor-suppressive properties of EDNRB overexpression." (PMID 38205153, 2024). "Similarly, the reported normal endothelial cell marker EDNRB characterizes aerocyte capillary endothelial cells, both in tumor and in healthy tissue." (PMID 37291214, 2023). "Here, a significantly decreased expression of Dnmt1 and Dnmt3b was recorded early after tumor cell implantation, which indicates a reduced DNA-methylating activity and could explain the increased expression of EdnrB and/or Ece1 mRNA." (PMID 32194414, 2020). "EDNRB, a G protein-coupled receptor, is also closely related with tumor." (PMID 31106044, 2019). "In SKCM, which has the highest mutation burden among TCGA tumor types, the most highly overexpressed GPCRs (GPR143, EDNRB, and GPR56) are mutated in <2% of SKCM tumors, whereas frequently mutated GPCRs (e.g., GPR98, mutated in nearly 40% of tumors) typically have low expression." (PMID 31765370, 2019). "To assess the relevance of EDNRB for paracrine protection in vivo, we co‐injected A375‐T cells with A375 control cells or with A375‐shEDNRB cells into zebrafish embryos, and monitored cell death within tumours in the absence or presence of BRAF inhibitor." (PMID 28606996, 2017). "Consequently, significantly lower level of EDNRB mRNA was found in CRC tumor samples than in normal samples (0.31 ± 0.91 versus 0.70 ± 1.18, p = 0.032)." (PMID 24326135, 2013). "This might imply that aberrant EDNRB methylation and conventional tumor markers could serve as complementary markers in the CRC diagnosis, although further work is needed to confirm our hypothesis." (PMID 24326135, 2013). "This suggests that a decrease of EDN3 expression accompanied by an increase of EDNRB expression may be a particular feature of gynaecological tumour entities." (PMID 19527488, 2009). "CmRT–PCR was used to verify the differential expression of EDNRB in the tumours used in SSH." (PMID 12439722, 2002). "Importantly, downregulation of endothelin receptor type B was observed in human tumor cells." (PMID 19812696, 2009). "Future efforts must prioritize EDNRB molecular profiling to balance efficacy and safety, advancing personalized ERA-based regimens for fibrotic and neoplastic diseases." (PMID 40589973, 2025). "Eight genes were differentially expressed at both the mRNA and protein levels, with ASCL1, EDNRB, INSM1, SOX11, SOX4, SOX8, and SIX1 showing reduced expression in tumor tissues, and CTNNB1 showing increased expression compared with para-cancer tissues." (PMID 40771813, 2025). "Beyond fibrosis, EDNRB dysregulation influences cancer progression: low EDNRB expression promotes metastasis via ERK pathway activation, whereas bosentan suppresses tumor cell migration by 62% and reverses epithelial-mesenchymal transition." (PMID 40589973, 2025). "We therefore assessed EDNRA expression in the A375 xenografts and found that although it was expressed at much lower levels than EDNRB, its expression was up‐regulated in BRAF inhibitor‐treated tumours." (PMID 28606996, 2017). "Similar to what we observed with bosentan, BRAF inhibitor/BQ788‐treated tumours displayed increased expression of MITF and EDNRB." (PMID 28606996, 2017). "One recent study found that using a combination of an antibody-drug conjugate targeting EDNRB, together with small-molecule inhibitors of the MAP kinase pathway, increased anti-tumor activity in BRAF/NRAS mutant cell lines and tumor models." (PMID 27148356, 2016).
tumor (continued). "To date, the understanding of the roles of NMRGs in immunomodulation remains limited, with preliminary preclinical findings suggesting the involvement of EDNRB and C3AR1 in modulating immune escape, and immune cells infiltration to tumour microenvironment in GBM." (PMID 41301734, 2025). "In this study, the expression of FAM110B was positively correlated with various immune checkpoints such as PDCD1, CTLA4, EDNRB, TLR4, etc., indicating that FAM110B may be a new target for tumor immunotherapy." (PMID 39170745, 2024). "While EDNRB and FMN2 as well as TBXT and ZNF671 could have potential tumor suppressor functions, MOS is a well-known oncogene." (PMID 38643219, 2024). "The sub‐clustering of ECs revealed six subtypes, including extra‐alveolar capillary EC (cEC) (FCN3+EDN1+PLVAP+), alveolar cEC (HPGD+EDNRB+IL1RL1+), arterial EC(GJA5+FBLN5+DKK2), lymphatic EC (CCL21+TFF3+FABP4), INSR+ tumour EC (INSRhiHSPG2+PLVAP+), and ACKR1+ tumour EC (ACKR1+SELP+IL1R1+)." (PMID 35184398, 2022). "Interestingly, a subcluster of Endo-1 was found almost exclusively in the tumor compartment, preferentially expressing known endothelial tip cell genes (KCNE3, DLL4, EDNRB, ANGPT2, and SERPINE1)." (PMID 36180422, 2022). "The LC-BC CCPs formed have no more than 12 nodes and identified only seven genes (EDNRB, CDKN2A, VEGFD, FOS, GNG11, TGFBR2, and BIRC5) compromised in signaling pathways associated with the acquisition of tumor characteristics." (PMID 36101460, 2022). "The relative expression of EDNRB in the 33 tumours showed a non-normal distribution, with a median of 27.4% (range 4.4–76.4%)." (PMID 12439722, 2002). "CD36 also demonstrated positive correlations with immune checkpoint molecules, including C10orf54, EDNRB, TLR4, ENTPD1, IL10, and IL2RA, suggesting that it may contribute to immune escape mechanisms by engaging checkpoint pathways in the tumor microenvironment." (PMID 41550652, 2025). "EDNRB expression did not correlate with largest basal tumour diameter." (PMID 12439722, 2002). "We did not detect any changes to the EDNRB gene copy number in any of nine tumours analysed." (PMID 12439722, 2002).
cancer (88 papers, 2002 to 2026). A tumor composed of atypical neoplastic, often pleomorphic cells that invade other tissues. "Numerous studies have established a close association between aberrant expression of the EDNRB gene and cancer occurrence, development, and prognosis, underscoring its importance in cancer biology." (PMID 38205153, 2024). "Methylation inactivation of EDNRB (endothelin receptor type B) was linked with the development ofprostate cancer, but the inactivation of this gene may be responsible for the progression of EOC." (PMID 30970615, 2019). "In light of previous findings in various cancers, we investigate whether EDNRB gene promoter methylation contributes to the risk of CRC in Chinese population." (PMID 24326135, 2013). "EDNRB’s mechanistic role and observed IPF-cancer connections warrant functional studies to establish causality." (PMID 40589973, 2025). "Although the therapeutic potential of targeting EDNRB in cancer has been explored, only one clinical trial focused specifically on EDNRB inhibition (NCT02442466)." (PMID 40597436, 2025). "Immunohistochemistry showed that key markers identifying this putative Tr-CAF subset—CXCL14, ADAMDEC1, EDNRB, and PROCR—were predominantly localized to fibroblasts within normal colonic mucosa and less frequently in cancer-associated fibroblasts (CAFs)." (PMID 40759242, 2025). "CELSR3, GPR25, EDNRB, and F2RL2 are significantly associated with patients’ survival in four cancers each, with an equal prevalence for lower and higher survival." (PMID 38723607, 2024). "Endothelin receptor type B (EDNRB) is usually underexpressed or even silenced by promoter hypermethylation in various human cancers by acting as an oncosuppressor." (PMID 34888137, 2021). "Cancers with lower EDNRB expression and higher EDN3 expression would be expected to have most EDNRB receptors saturated by ET3, preventing any ET1-stimulated signaling effects." (PMID 32201539, 2020). "Our observation that in the TCGA dataset, only EDNRB-532 alters survival in basal cancers is consistent with our data showing EDNRB-532 promotes cell viability." (PMID 32201539, 2020). "For example, ET3 expression is suppressed in breast, colon cancer and cervical cancer 21, 22, 23, 24, suggesting an inhibitory role of ET3/EDNRB signaling in these cancers." (PMID 32201539, 2020). "Concurrent ETAR inhibition with macitentan and EDNRB re-expression produces a significant antinociceptive effect in two separate mouse cancer models." (PMID 33257729, 2020). "EDNRB is a G protein-coupled receptor that activates a phosphatidylinositol-calcium second messenger system, and is also closely related with cancer." (PMID 31106044, 2019). "EDNRA and EDNRB have also been found expressed in endothelial cells in different human tumors and a role in angiogenesis and cancer metastasis has been reported." (PMID 29349517, 2018). "Endothelin ligands (ET-1, ET-3) and receptors (EdnrA, EdnrB) form the endothelin axis, which participates in diverse biological processes including development, inflammation and cancer." (PMID 26061883, 2015). "Some reports have focused on the correlation between EDNRB methylation and cancer clinical features." (PMID 24326135, 2013). "Despite this setback, the role of EDNRB in cancer biology remains promising." (PMID 40597436, 2025). "Similarly, EDNRB expression exhibited cancer cell‐specific elevation, particularly in NCI‐N87 cells." (PMID 40245183, 2025). "Conversely, re-expression of EDNRB can alleviate cancer-induced pain." (PMID 38205153, 2024). "Furthermore, PDE2A expression in most cancers was positively associated with PDCD1, EDNRB, ADORA2A, TGFB1, and especially C10orf54." (PMID 39699377, 2024). "EDNRB was identified as a G-protein coupled receptor that activates the phosphatidylinositol calcium signaling cascade and is also reported to be aberrantly expressed and differentially methylated in cancer." (PMID 38643219, 2024).